BICDL3P (BICD family like 3, pseudogene)
Synonyms: NCRNA00035; formerly WBSCR26; LINC00035; ABHD11-AS1
Gene: Transcribed unitary pseudogene on chromosome 7 (73,735,407 to 73,736,073, forward strand). Ensembl gene ENSG00000225969.
Diseases named in the same sentence as BICDL3P in open-access papers:
BICDL3P is named in the same sentence as 2 diseases in open-access papers, as found by Europe PMC text mining. Sharing a sentence is not in itself a finding about the gene and the disease.
BICDL3P shares sentences with these, for which no sentence is quoted: Huntington disease (1 paper); ovarian carcinoma (1).